ANXA1 (annexin A1)
Diseases named in the same sentence as ANXA1 in open-access papers (continued):
Sharing a sentence is not in itself a finding about the gene and the disease.
glioma (continued). "For example, ANXA1 was reported to regulate glioma cell apoptosis." (PMID 37841425, 2023). "Finally, immunohistochemistry analysis showed an obvious correlation between ANXA1 expression and Ki-67 in glioma tissues." (PMID 35415239, 2022). "After an analysis of the potential molecular targets of glioma, we found that ANXA1 may play an important role in glioma through ECM–receptor interaction and focal adhesion signal pathways." (PMID 35711921, 2022). "Moreover, we collected the sample tissues and corresponding paracancerous tissues of 23 glioma patients and then conducted a Western blot experiment to verify the expression and correlate survival of ANXA1." (PMID 35711921, 2022). "Moreover, we found that ANXA1 promotes glioma cell growth by activating the p65 and Akt signalling pathways." (PMID 35415239, 2022). "Our research showed that ANXA1 is translocated to the nucleus in glioma cells exposed to TNF-α." (PMID 35415239, 2022). "ANXA1 had just been reported as a prognostic and immune microenvironmental marker in glioma." (PMID 36111134, 2022). "In addition, the expression of ANXA1 was investigated according to the clinical case characteristics of glioma, and a clinical correlation nomogram was constructed using the CGGA database, which supported that ANXA1 was an important predictor of glioma." (PMID 35711921, 2022). "In the analysis of KEGG and Gene Set Enrichment Analysis (GSEA), it is shown that ANXA1 may play an important role in glioma patients by affecting extracellular matrix (ECM)–receptor interaction and the focal adhesion signal pathway." (PMID 35711921, 2022). "Moreover, high expression of ANXA1 were associated with high WHO grade, as well as high CD1a and PD‐L1 expression in gliomas." (PMID 35770335, 2022). "We then explored the regulatory mechanism of ANXA1 and its role in glioma cell proliferation." (PMID 35415239, 2022). "Based on this property, we explored whether ANXA1 translocates to the nucleus in glioma cells treated with TNF-α." (PMID 35415239, 2022). "Survival prognosis, ROC curve, and univariate and multivariate Cox regression analyses were performed using the CGGA and TCGA databases, which further showed that ANXA1 played an important role in the development of glioma and supported that ANXA1 was an independent prognostic index of glioma." (PMID 35711921, 2022). "Finally, we detected ANXA1 expression in primary clinical specimens and samples from the CGGA database and found that ANXA1 correlated positively with Ki-67 and was highly expressed in high-grade gliomas." (PMID 35415239, 2022). "Moreover, we found that the prognosis of glioma patients with a high ANXA1 expression was worse and that ANXA1 was an independent prognostic index of gliomas." (PMID 35711921, 2022). "Therefore, we investigated the expression of the ANXA1 gene in glioma and found that ANXA1 was overexpressed in gliomas." (PMID 35711921, 2022). "Younger patients with glioma had lower expression of ANXA1 (p < 2.14e-10)." (PMID 34912807, 2021). "In addition, due to the genetic and clinical differences between IDH-mutated gliomas and IDH wild-type gliomas, we explored the role ANXA1 played in gliomas with different IDH statuses." (PMID 34912807, 2021). "In the single-cell level, our result showed that tumor cells with high expression of ANXA1 are in the MES cellular state, indicating that ANXA1 could drive transitions to MES-like states in gliomas as reported in a previous study." (PMID 34912807, 2021). "Further studies are warranted to confirm ANXA1 as a potential immunotherapeutic target for gliomas." (PMID 34422796, 2021). "Gliomas in Dataset 1 were ordered by increasing ANXA1 expression." (PMID 34912807, 2021). "Our work provides an insight on ANXA1’s role in glioma, which might translate to clinical application for future diagnosis and therapy in glioma." (PMID 34912807, 2021).
glioma (continued). "Finally, in vitro experiments verified that antagonizing ANXA1 expression promoted cell apoptosis and inhibited the invasion and migration capacities of glioma cells." (PMID 34422796, 2021). "Glioma patients with higher ANXA1 expression, including LGG and GBM samples, had a significantly shorter survival rate than those with a lower expression from the TCGA database (P < 0.05); The survival analysis results of CGGA were consistent with those of TCGA (P < 0.01)." (PMID 34422796, 2021). "Gliomas with chemotherapy and/or radiotherapy tend to have a high ANXA1 expression." (PMID 34912807, 2021). "Furthermore, ANXA1 level was positively correlated with the histopathological factors and negatively related to the survival of glioma patients based on the analysis of multiple databases." (PMID 34422796, 2021). "ANXA1 inhibition needs to be explored further in vitro and in vivo to better understand the efficacy of targeting this protein in suppressing growth and tumor progression of glioma." (PMID 34422796, 2021). "In particular, we found that these coexpressed genes also positively function in apoptosis, epithelial–mesenchymal transition, NF-κB signaling, etc., indicating that ANXA1 may play an important role in regulating cell fate in gliomas." (PMID 34912807, 2021). "Importantly, in our analysis from 1018 CGGA samples, higher ANXA1 expression predicted a poor prognosis in gliomas." (PMID 34912807, 2021). "The in vitro experiments showed that suppressing ANXA1 expression could significantly inhibit the proliferation and motility of glioma cells and promote cell death via apoptosis." (PMID 34422796, 2021). "In a recent study, a high expression of FPRs overlapped the AnxA1 immunolocalization in gliomas." (PMID 34650406, 2021). "These experimental results suggested that the inhibition of ANXA1 expression could reduce the metastatic potential of gliomas, which further verified that ANXA1 expression was related to malignancy in gliomas." (PMID 34422796, 2021). "Taken together, these results suggest that the ANXA1 gene acts as an oncogene and may serve as a biomarker for disease progression in gliomas." (PMID 34912807, 2021). "The ANXA1 expression was highest in IDH wild-type and lowest in IDH mutation and 1p/19q co-deletion in LGGs (all p ≤ 5e-5), while ANXA1 expression was higher in the IDH wild-type than in IDH mutant gliomas in GBMs (p < 5e-11)." (PMID 34912807, 2021). "In gliomas, although there had been several reports confirming the overexpression of ANXA1 and that it may be a prognostic and immune microenvironmental marker, the exhaustive functions of ANXA1 in gliomas remain unclear." (PMID 34912807, 2021). "Gliomas with lower ANXA1 expression are more likely to belong to proneural (PN) and neural (NE) subtypes and have a good prognosis, while gliomas with high ANXA1 expression are more likely to belong to mesenchymal (MES) and classical (CL) subtypes and have poor survival (all p < 2.00e-16)." (PMID 34912807, 2021). "ANXA1 expression was heterogeneous in different glioma subtypes." (PMID 34912807, 2021). "In addition, we found that M2 macrophages are significantly enriched in gliomas with high ANXA1 expression." (PMID 34912807, 2021). "Therefore, ANXA1 due to its immune-related functions, can be an important prognostic indicator and immune microenvironmental marker for gliomas." (PMID 34422796, 2021). "We found that ANXA1 is closely related to the malignant progression in gliomas." (PMID 34912807, 2021). "Our results showed that primary gliomas and LGGs had lower levels of ANXA1 expression (all p < 0.01), suggesting that ANXA1 may play a positive role in malignant progression." (PMID 34912807, 2021). "However, the systematic and comprehensive transcriptome characterization of ANXA1 in gliomas is unclear." (PMID 34912807, 2021). "Finally, we provided evidence that Anxa1 is required for FoxM1-induced gliomas progression in model mice." (PMID 23991102, 2013).
glioma (continued). "Moreover, overexpression of Anxa1 in depleted FoxM1 glioma cells recovered the ability of tumorigenicity." (PMID 23991102, 2013). "Furthermore, we found that FoxM1 promote glioma cells proliferation, migration, and angiogenesis by directly regulating Anxa1 expression." (PMID 23991102, 2013). "Therefore, FoxM1 overexpression contributes directly to Anxa1 overexpression in glioma cell proliferation, migration and angiogenesis." (PMID 23991102, 2013). "Furthermore, we performed transwell assays to assess the function role of FoxM1/Anxa1 in glioma cells migration." (PMID 23991102, 2013). "In addition, a strong correlation of the co-expression of FoxM1 and Anxa1 were observed in patients with gliomas." (PMID 23991102, 2013). "Therefore, our study provides both clinical and mechanistic evidences that FoxM1 directly regulates Anxa1 expression and showed a novel mechanism by which FoxM1 promotes glioma proliferation, migration and angiogenesis." (PMID 23991102, 2013). "Anxa1 is overexpression in patients with hepatocellular carcinoma, gliomas, and adenocarcinomas of the esophagus and pancreas, but loss of expression in adenocarcinoma of the breast and prostate, as well as in squamous cell carcinoma of the esophagus and head and neck." (PMID 23991102, 2013). "Moreover, we showed that FoxM1 promotes Anxa1 transcription in human glioma cells and Anxa1 is required for FoxM1-induced cell proliferation, migration and angiogenesis." (PMID 23991102, 2013). "The results indicated Anxa1 mRNA expression was up-regulated in all glioma specimens." (PMID 23991102, 2013). "This suggests that Anxa1 might be involved in the glioma progression, although the full functional role therein remains unclear." (PMID 23991102, 2013). "Importantly, ANXA1 expression correlated with higher-grade gliomas and poor patient prognosis." (PMID 38639785, 2024). "Moreover, the overexpression of ANXA1 in glioma was verified by Western blotting analysis." (PMID 35711921, 2022). "In addition, we evaluated 23 glioma sample tissues and their corresponding paracancerous tissues by Western blot analysis, and the results showed that the ANXA1 expression levels were significantly higher in the 23 glioma sample tissues than their corresponding paracancerous tissues (p < 0.05)." (PMID 35711921, 2022). "Finally, by using gene correlation analysis, we found that the COL1A1, COL1A2, FN1, ITGA1, ITGB1, and ANXA1 genes may play a synergistic role in glioma patients." (PMID 35711921, 2022). "In addition, knockdown of ANXA1 slowed glioma cell proliferation." (PMID 35415239, 2022). "Therefore, the present study using public data recommends that ANXA1 may be an important molecular target for glioma." (PMID 35711921, 2022). "In addition, gliomas with chemotherapy and/or radiotherapy tend to have a high ANXA1 expression." (PMID 34912807, 2021). "Compared with the previous studies, we revealed that ANXA1 was also upregulated in M2 macrophages derived from the glioma immune microenvironment, indicating that ANXA1 may exert pro-tumor and inhibitory immune effects in both tumors intrinsically and the tumor microenvironment." (PMID 34912807, 2021). "ANXA1 may become a valuable factor for the diagnosis and treatment of gliomas in clinical practice." (PMID 34912807, 2021). "Therefore, our results suggest that Anxa1 expression related to FoxM1 expression in human glioma tissues and the Anxa1/FoxM1 expression might be useful to predict the outcome in patients with glioblatoma." (PMID 23991102, 2013). "The production of signaling factors (PNT, MIF, ANXA1, and MDK) in MAN1C1-expressing glioma cells enables communication with microglial/myeloid cell clusters." (PMID 39333557, 2024). "Secreted signals in MAN1C1-expressing glioma cells, such as PTN, MIF, ANXA1, MDK, and NAMPT, allowed MAN1C1 to interact with myeloid/microglial cells." (PMID 39333557, 2024).
glioma (continued). "The purpose of this study was to explore the regulatory mechanism of Annexin A1 (ANXA1) in glioma cells in the inflammatory microenvironment induced by tumour necrosis factor α (TNF-α) and its effects on glioma cell proliferation." (PMID 35415239, 2022). "The results demonstrated that ANXA1 was overexpressed in gliomas with higher expression in GBM samples than in LGG samples (p < 0.05), supporting that ANXA1 is correlated with a higher grade of gliomas." (PMID 35711921, 2022). "In summary, our study elaborates on the possible mechanism of ANXA1 in the inflammatory microenvironment of glioma cells upon TNF-α stimulation and the role of ANXA1 in glioma cell proliferation." (PMID 35415239, 2022). "Our current study confirms that ANXA1 is overexpressed in human GBM at both mRNA and protein levels and is correlated with high glioma grade and poor outcome." (PMID 35770335, 2022). "For verification, we used samples from the CGGA database to determine the relationship between ANXA1 and TNFR1, and a positive correlation between ANXA1 and TNFR1 gene expression was observed in both primary and recurrent glioma samples." (PMID 35415239, 2022). "Recent studies proved that targeting ANXA1 abrogated Treg-mediated immune suppression in triple-negative breast cancer, and ANXA1 was considered a worse prognostic and TME marker in gliomas." (PMID 36246597, 2022). "However, ANXA1 expression is upregulated in malignant glioma tissues; it is secreted by necrotic glioma cells, and abnormal levels of ANXA1 in the tumour microenvironment can activate formyl peptide receptor 1 to enhance the proliferation and invasion of glioma." (PMID 35415239, 2022). "However, the biological role and clinical behavior of ANXA1 in glioma remain unclear." (PMID 34912807, 2021). "A series of genes such as EN1, S100A4, ANXA1, PDPN, IGFBP2 and CHI3L1 were upregulated in radiotherapy treated glioma patients, while other genes such as PRLHR, SFRP2, BRINP1, TRIM67, LHX5, KCNIP2 and NSG2 were downregulated." (PMID 34852024, 2021). "Many studies have reported the role of ANXA1 and SOD2 in gliomas, by virtue of their increased expression levels in the tumor tissues." (PMID 34055594, 2021). "The result showed that ANXA1 and CD274 expression (patient id:122; 3,226) were positive in high grade gliomas, and there is a certain correlation between their expressions." (PMID 34422796, 2021). "Overall, these findings have proved that ANXA1, a key gene in the TME, can be an effective target for treatment of glioma." (PMID 34422796, 2021). "We have also validated tumor markers such as CLU and CST3 for Meningioma, ANXA1 and SOD2 in Glioma and MAP2 for Medulloblastoma." (PMID 34055594, 2021). "In this study, we revealed that ANXA1 was significantly upregulated in GBM patients, especially enriched in IDH wild-type gliomas, which was consistent with previous reports." (PMID 34912807, 2021). "We observed that the levels of peptides for ANXA1 and SOD2 were upregulated in glioma tissues in comparison to peritumoral control tissues." (PMID 34055594, 2021). "We found that the expression values of ANXA1 were significantly higher in GBM patients than in those with normal brain and lower-grade gliomas (WHO II and WHO III) in Dataset 1 (p < 5e-5)." (PMID 34912807, 2021). "ANXA1 was shown to promote GBM tumor growth and progression and is more highly expressed in poorly differentiated human primary gliomas compared with lower grade tumors." (PMID 32070274, 2020). "Previous studies have shown that tumour cells from highly malignant human glioma specimens express FPR-1; subsequently it has been shown that ANXA1 released by necrotic human glioblastoma cells was able to stimulate tumour cell growth through FPR-1." (PMID 25510623, 2014). "As the P65 and Akt signalling pathways contribute to the proliferation of glioma cells stimulated with TNF-α, we sought to determine whether these signalling pathways are regulated by ANXA1." (PMID 35415239, 2022).
glioma (continued). "ANXA1 is useful as a prognostic biomarker in lower grade glioma patients with MGMT promoter methylation and a prognostic indicator and an immunotherapy marker for the tumour microenvironment in glioma." (PMID 35415239, 2022). "In contrast, we found that coexpressed negative genes of ANXA1 participate in the neuro-basic functions in gliomas, such as synapse structure and organization, regulation of cellular component biogenesis, and neuro-projection morphogenesis and differentiation." (PMID 34912807, 2021). "We found annexin A1 (ANXA1) by evaluating the immune microenvironment of the glioma samples from The Cancer Genome Atlas (TCGA), and further verified the finding using Chinese Glioma Genome Atlas (CGGA) databases and in vitro experiments." (PMID 34422796, 2021). "ANXA1 is differentially expressed in a variety of tumors and a number of genome-sequencing studies have shown that ANXA1 is highly expressed in gliomas, but intensive research on ANXA1 function in glioma was lacking." (PMID 34422796, 2021). "ANXA1 and CD276 (Patient id: 3,174; 3,241) also were overexpressed in high grade gliomas." (PMID 34422796, 2021).